MIR490 (microRNA 490)
Synonyms: hsa-mir-490; miR-490; MIRN490
Gene: MicroRNA gene on chromosome 7 (136,903,167 to 136,903,294, forward strand). Ensembl gene ENSG00000207597.
Gene Ontology:
Biological process: miRNA-mediated post-transcriptional gene silencing
Cellular component: RISC complex
Homologues: Orthologues: chimpanzee ptr-mir-490 (100% identical), macaque mml-mir-490 (100% identical), mouse Mir490 (63% identical), rat Mir490 (63% identical), dog MIR490 (62% identical), guinea pig MIR490 (61% identical), pig ssc-mir-490-1 (59% identical), rabbit ocu-mir-490 (46% identical).
Diseases named in the same sentence as MIR490 in open-access papers:
MIR490 is named in the same sentence as 5 diseases in open-access papers, as found by Europe PMC text mining. Sharing a sentence is not in itself a finding about the gene and the disease. The quoted sentences say what the papers report.
lung carcinoma (1 paper, 2020). "In the transcriptome of our EVs, we found also MIR490 that seems to have the role of tumor suppressor in lung cancer cells A549 and ovarian cancer by blocking the transcription of CCND1 and CDK1 respectively, two important genes involved in cell cycle progression." (PMID 32582296, 2020).
MIR490 also shares sentences with these, for which no sentence is quoted: bladder cancer (1 paper); osteosarcoma (1); ovarian carcinoma (1); tumor (1).